CD4 (CD4 molecule)
Diseases named in the same sentence as CD4 in open-access papers (continued):
Sharing a sentence is not in itself a finding about the gene and the disease.
cardiac hypertrophy (16 papers, 2012 to 2025). "Moreover, deficiency of CD4+ T cells by TCR-α KO significantly attenuated TAC-induced cardiac hypertrophy, fibrosis, and dysfunction through attenuating interferon-γ dependent cardiac fibroblast activation and proliferation." (PMID 39324134, 2024). "T cells mainly comprise CD8+ T and CD4+ T cells, with CD4+ T cells playing a more critical role in cardiac hypertrophy." (PMID 33324685, 2020). "Among the T-cell subpopulations, it appears that the CD4+ T-cells are the dominant immune mediators involved in the remodeling process that occurs in the postischemic myocardium and in maladaptive myocardial hypertrophy via the release of fibrosis promoting cytokines such as IL-4 and IL-13." (PMID 39273110, 2024). "Taken together, these data demonstrate that the splenic expression of CD4+ T cell Xbp1s is recovered by removal of the 2 hits of HFpEF in vitro and in vivo, and results in ameliorated CD4+ T cell cardiac infiltration and cardiac hypertrophy as well as partial improvement in diastolic dysfunction." (PMID 37874641, 2023). "Moreover, CD4+ T cells play a pivotal role in pathological cardiac remodeling, which predominantly induces cardiac hypertrophy by promoting myocardial fibrosis." (PMID 35687056, 2022). "However, during chronic HF (8-week post-MI) another cascade of CD4+ T-cell activation ensues which coincides with pathological LV remodeling and cardiac hypertrophy." (PMID 36093172, 2022). "Our data in wild-type mice uncover that CD4+ effector T cells are expanded in the lymphoid organs close and distal to the heart and infiltrate the heart shortly after mice are fed H/L in experimental cardiometabolic HFpEF, coexisting with cardiac hypertrophy and diastolic dysfunction." (PMID 37874641, 2023). "In these mice, cardiac hypertrophy and systolic blood pressure were reduced in comparison with mice remaining on H/L throughout the duration of the experiment, and these changes were guided by partial reversal of CD4+Xbp1s downregulation and subsequent decline in cardiac T cell infiltration." (PMID 37874641, 2023). "Indeed, the deleterious effects of cardiac infiltration of CD4+ T cells have also been witnessed in pressure overload-induced cardiac hypertrophy and fibrosis, which could be depressed by genetic inactivation of CD4+ T cells." (PMID 32327611, 2020). "We report that both CD4+ and CD8+ T cells are increased in the heart in response to H/L, yet we do not interrogate their relative contribution to diastolic dysfunction and cardiac hypertrophy." (PMID 37874641, 2023). "Collectively, in addition to maintaining the proportion of Treg cells among the CD4+ T cells or enhance their immunosuppressive functions, modulating Th1/Th2 (or Th1/Th2 cytokines ratio) balance may also be an effective strategy to regulate cardiac hypertrophy and suppress inflammatory response." (PMID 33324685, 2020).
contact dermatitis (16 papers, 2015 to 2025). An inflammatory skin condition caused by direct contact between the skin and either an irritating substance or an allergen. "It has been known that CD4+ or CD8+ T cells are associated with contact dermatitis induced by DNFB." (PMID 32967214, 2020). "Research has shown that LCs induce CD4+ regulatory T lymphocytes, and promote tolerance in CD8+ T lymphocytes, and cause production of IL-10 by Langerhans cells which suppress contact dermatitis." (PMID 38500882, 2024). "Contact dermatitis: Application of haptens onto the skin can elicit a sensitization of T cells (CD4 and CD8) and a contact dermatitis, which is an inflammatory skin disease." (PMID 35386664, 2022). "Urushiols are pro-electrophilic haptens that cause severe contact dermatitis mediated by CD8+ effector T-cells and downregulated by CD4+ T-cells." (PMID 34711292, 2021). "The model developed spongiotic edema with intra- and peri-epithelial infiltration of CD4+ T cells in the inflamed skin that resembles human contact dermatitis." (PMID 32517103, 2020). "Expression of CD68 and CD4 was greatly enhanced in response to stimulation by OXA; however, treatment with ghrelin drastically attenuated the secretion of CD68 and CD4, implying a reduced severity of contact dermatitis in mice." (PMID 30718736, 2019). "Experimental contact dermatitis consists of the early phase dominated by complement and innate immune cells and the delayed phase governed by adaptive immune cells, such as CD4+ T cells (Th1 and Th2 cells), CD8+ T cells (Tc1 cells), and B cells, as a typical type IV allergic response." (PMID 36768979, 2023). "MCR signaling has been reported to transform CD4 + T effector cells into CD4 + CD25 + Tregs and reactive CD8 + cells in tolerogenic type in murine contact dermatitis." (PMID 38110615, 2023). "The treatment of mice subjected to contact dermatitis with polyphenols from pomegranate was followed by increasing splenic IL-10-producing and IFN-γ-/IL-4-producing CD4+ T cells." (PMID 36431972, 2022). "PIP binds to CD4 and inhibits the CD4-HLA-DR interaction, induces differentiation of naive T cells into CD4(+) CD25(+) forkhead box P3(+) (FOXP3(+)) Treg cells, and exerts both local and systemic immunosuppressive effects in mouse contact dermatitis." (PMID 39938773, 2025). "In the contact dermatitis mouse model, nuclear translocation of K17 facilitates the activation and nuclear translocation of signal transducer and activator of transcription 3 (STAT3) activating CCL20 production and CD8+ and CD4+ T cell trafficking to skin lesions." (PMID 38730319, 2024).
cyst (16 papers, 2015 to 2025). A sac-like closed membranous structure that may be empty or contain fluid or amorphous material. "The cyst number in the liver was significantly increased in CD4 T-cell-deficient mice compared to WT mice (P <0.001) (–C)." (PMID 36046744, 2022). "All these data suggest that only the response to E. granulosus antigens as AgB-specific triple functional IL-2+TNF-α+Th2+ cytokines and double functional TNF-α+Th2+ cytokines CD4+ T-cells associated with cyst biological activity." (PMID 26575186, 2015). "In summary, our findings showed that T cells were involved in the formation of the immune environment in the liver in CE patients and E. granulosus s.s.-infected mice, with CD4+ T cells being the dominant immune cells; this process was closely associated with cyst viability and establishment." (PMID 36046744, 2022). "Moreover, CD8 T cells were the most represented population in cattle progressive cysts, whereas CD4 T cells are associated with regressive cysts, thus suggesting that the lymphocytes that are locally activated may have an impact on cyst evolution." (PMID 38921775, 2024). "After transfer of adoptive CD4+ T cells, the size and weight of cyst in the abdominal cavity of CD4+T+rEg.P29+CpG+Infection group were also reduced compared with those in the CD4+T+PBS+Infection group and CD4+ T+CpG+Infection group." (PMID 38151996, 2023). "Flow cytometric analysis of the lymphocyte populations confirmed that the cyst cells were CD4+ or CD8+ mature T cells." (PMID 30143634, 2018). "We demonstrate that IL-2+TNF-α+Th2+ triple-positive AgB-specific CD4+ T-cells and TNF-α+Th2+ double-positive AgB-specific CD4+ T-cells associate with cyst biological activity, being significantly increased in the active CE stages." (PMID 26575186, 2015). "Test performance varied by both host CD4 count and cyst stage." (PMID 41003557, 2025). "We then tested whether test performance is influenced by immune status (CD4 count), clinical stage, time on antiretroviral therapy, or cyst characteristics." (PMID 41003557, 2025). "Herein, we aim to investigate the expression of CD4 + /CD8 + T cells and GrB in surgically resected hydatid cyst cases and to associate their expression with hydatid cyst fertility to clarify the immunological mechanisms underlying cyst fertility." (PMID 38072840, 2023). "The results show the cyst inhibition rate is 41.52% after adoptive transfer of CD4+ T cells." (PMID 38151996, 2023). "If IFN-γ production by infiltrated CD4+ and CD8+ T cells in the brain is required for the prevention of cerebral tachyzoite growth, anti-cyst activity of CD8+ T cells requires perforin in conjunction with microglia and macrophages help." (PMID 33324583, 2020). "Our results showed that the percentage of CD4+ and CD8+ T cells was significantly increased following DNA immunization with pVAX-IST and/or pVAX-NSM, suggesting the activation of T lymphocytes and limiting tissue cyst formation in the brain." (PMID 39597646, 2024). "Pc cysts were readily detected in the lungs of the Pc-susceptible strains at 4 and 6 weeks post inoculation, while no cyst forms were found in the lungs of CD4-depleted FVB mice." (PMID 30283457, 2018). "CD4 + T and CD8 + T cells are essential inflammatory components in hydatid cysts independent of cyst types." (PMID 38072840, 2023).
granulomatosis with polyangiitis (16 papers, 2004 to 2025). A small-vessel necrotizing vasculitis characterized by the association of inflammation of the vessel wall and peri- and extravascular granulomatosis. "Over the years, CD4+CD28− T cells have been shown to be implicated in various inflammatory conditions including granulomatosis with polyangiitis (GPA), where CD4+CD28− T cells were linked to increased infection and mortality." (PMID 28303136, 2017). "Co-trimoxazole is commonly used for PCP prophylaxis in Wegener's granulomatosis when CD4+ counts are <300 cells/mm3 or even with normal counts in some centres." (PMID 15488151, 2004). "Persistent expansion of circulating CD4+ effector memory T cells (TEM) in patients with granulomatosis with polyangiitis (GPA) suggests their fundamental role in disease pathogenesis." (PMID 28615072, 2017). "In ANCA-associated vasculitis, CD28 was found to be downregulated on circulating and lesional CD4+ T- cells and CD4+CD28- T-cells have been described as the major source of pro-inflammatory cytokines (particularly IFN-γ and TNF-α) in Wegener’s Granulomatosis." (PMID 28991896, 2017).
hemophilia A (16 papers, 2013 to 2024). The most common form of hemophilia characterized by spontaneous or prolonged hemorrhages due to factor VIII deficiency. "An interesting observation is that low CD4 T cells resulting from HIV infection of hemophilia A patients was associated with less anti-FVIII antibodies, suggesting an important role of T cell help." (PMID 32793213, 2020). "To accomplish this, we adoptively transferred CFSE-labeled OTII CD4 T cells into hemophilia A (TKO) recipients, followed by exposure to FVIII-OVA." (PMID 35885029, 2022). "In contrast, multiple studies have sought to identify CD4 T cell epitopes of FVIII from severe hemophilia A patients, mild/moderate hemophilia A patients and FVIII-deficient humanized mice." (PMID 32793213, 2020). "Upon transfer of the FVIII-specific CD4+ FoxP3+ cells into hemophilia A mice, development of inhibitory antibodies in response to administering FVIII protein was completely suppressed." (PMID 30842776, 2019). "As a result, CD4+ T-cell responses in patients with severe hemophilia A are of polyclonal origin and directed against multiple epitopes." (PMID 24244658, 2013). "It should be noted that the clinical relevance of our findings is crucially dependent on the specificity and hierarchy of FVIII-specific CD4+ T cells present in hemophilia A patients, of which only limited data is available." (PMID 24244658, 2013). "For six out of all FVIII regions identified in this study and our previous work, reactive CD4+ T cells have been identified either in a hemophilia A patients or hemophilia mice." (PMID 24244658, 2013). "Emerging evidence implicates CD4+ T cell activation in mediating this autoimmune response, with their involvement like that observed in congenital hemophilia A. Several genes such as HLA II DRB*16, DQB1*0502, and CTLA-4 + 49 are responsible for the pathogenesis of AHA." (PMID 38920981, 2024). "Humoral immunity to factor VIII (FVIII) represents a significant challenge for the treatment of patients with hemophilia A. Current paradigms indicate that neutralizing antibodies against FVIII (inhibitors) occur through a classical CD4 T cell, germinal center (GC) dependent process." (PMID 35634288, 2022). "Furthermore, inhibition of CD4 T cell priming by blockade of costimulatory pathways prevented the generation of inhibitors in a mouse model of haemophilia A." (PMID 34567009, 2021). "Indeed, synthetic peptides encompassing the G99 epitope have been shown to stimulate CD4+ T-cell proliferation and induce an immune response, including residues 2301-2320, which had the strongest response among acquired hemophilia A patients." (PMID 34177966, 2021). "In this study, we hypothesized that forced FoxP3 expression in conventional/effector CD4+ T cells (Tconv/Teff) from hemophilia A mice that were immunized with FVIII would yield an enriched pool of FVIII specific suppressor Treg-like cells." (PMID 30842776, 2019). "The current findings may therefore assist in the search for FVIII-specific CD4+ T cells in hemophilia A patients and could thereby contribute to the development of FVIII variants with reduced immunogenicity." (PMID 24244658, 2013). "Several studies in hemophilia A patients and in murine models of hemophilia A suggested that FVIII-specific CD4+ T cells are crucial for the induction of neutralizing antibody responses against FVIII." (PMID 36389737, 2022). "In hemophilia A, several immune cells are involved in directing the immune response toward inhibitor development, and antigen presentations by APCs and subsequent activation of FVIII-specific CD4+ T cells appear to play a key role." (PMID 32351505, 2020). "In mild/moderate hemophilia A patients, the remaining material of FVIII circulating in the blood might exert selective pressure on the CD4 T cells in the thymus." (PMID 32793213, 2020).
hemophilia A (continued). "Therefore, we determined the frequency of both LAP+CD25−FoxP3− cells among circulating CD4+ T cells and LAP+ cells among circulating CD4+CD25+FoxP3+ cells in haemophilia A mice that received either preventive or interventional oral tolerance." (PMID 29106782, 2018). "The reduction of FVIII-specific CD4+ T cell activation, as well as amplification of regulatory subsets of T cells by IDO1 represents a potential mechanism for tolerance induction and a possible strategic means to restrain the anti-FVIII immune response in hemophilia A." (PMID 32351505, 2020). "When we used these tetramers in an HLA-DR15.01+ hemophilia A patient after successful ITI, we indeed detected a distinct subset of FVIII-specific CD4+ T cells, as opposed to an HLA-mismatched control patient." (PMID 36107620, 2022).
myeloid leukemia (16 papers, 2006 to 2025). A clonal proliferation of myeloid cells and their precursors in the bone marrow, peripheral blood, and spleen. "So far, STAT5B mutations are rare and tend only to be found in human myeloid leukemia such as CD4+ T-cell prominent granular lymphocytic (T-LGL) leukemia, chronic natural killer lymphoproliferative disorders (CLPD-NK), Acute promyelocytic leukemia (APL)." (PMID 36524006, 2022). "After reaching a resting state on day 10–12, transduced CD4+ T cells were re-stimulated with K562 (myelogenous leukemia line) target cells that were modified to express HLA-A2, GFP, and the NY-ESO-1 antigen." (PMID 23533620, 2013). "In vivoWEHI3B myeloid leukemia modelDC/EVs vaccination of tumour-bearing mice resulted in more significant retardation of tumour growth and survival in animals as compared with tumour lysate-loaded DCs.DC/EVs stimulated trogocytosis and proliferation of CD4+ T cells." (PMID 31680949, 2019). "The association between reduced mitochondrial activity and cytotoxic effects of ArtinM has been reported when stimulating a few cell types, such as murine CD4+ and CD8+ T cells, NB4 human myeloid leukemia cells, and Jurkat human leukemic T cells." (PMID 36674590, 2023). "Cells of the Jurkat cell line are human leukemic cells that originated as CD4-positive T lymphocytes, while THP-1 cells are human myeloid leukemia cells that were derived from a patient with acute monocytic leukemia and are often used for studying innate immune functions." (PMID 34069922, 2021). "Most surprisingly, similar increases in nucleosome occupancy were also seen on both regulated and non-regulated promoters during differentiation of human myeloid leukemia cells and upon activation of human CD4+ T-cells." (PMID 21853138, 2011).
plaque psoriasis (16 papers, 2017 to 2025). "Overall, IL-21 and its receptor were highly expressed in CD4+ T cells in the lesional skin of moderate-to-severe plaque psoriasis patients." (PMID 31440249, 2019). "Following subcutaneous administration of 9 doses of 60 mcg dalazatide over 4 weeks to patients with active mild-to-moderate plaque psoriasis, CD4+ TEM homing to the skin, were found to express lower levels of the T cell activation marker HLA-DR." (PMID 28723914, 2017). "Specifically, Patients 1 and 3, who had large-plaque psoriasis, had higher frequencies of IL - 17A-producing CD4+ and CD8+ T cells compared to Patient 2, who had small-plaque, follicular psoriasis and had a higher frequency of interferon (IFN)-γ-producing counterparts." (PMID 40969757, 2025). "CD4+T cells from patients with psoriasis vulgaris showed miR-200a and miR-210 over-expression." (PMID 30761124, 2019). "CD4+ T cells from patients with psoriasis vulgaris showed miR-210 over-expression." (PMID 30761124, 2019). "Interestingly, researcher found that two-thirds of patients with moderate-to-severe plaque psoriasis harbor CD4+ and/or CD8+ T cells specific for LL-37 infiltrating lesioned skin, which produce IFN-γ (Th1 cytokines), and CD4+ T cells also produce Th17 cytokines (IL-17, IL-21, and IL-22)." (PMID 32509872, 2020). "Investigation into Tc17 cell activation confirmed that CD8 + T cells are infiltrated in peripheral vascular walls and the subcutis in BD, and, concurrently, IL-17A + CD8 + T cells were elevated in BD compared to psoriasis vulgaris lesions and were a major source of IL-17A rather than CD4 + T cells." (PMID 34975900, 2021).